CLDN4 (claudin 4)
Diseases named in the same sentence as CLDN4 in open-access papers (continued):
Sharing a sentence is not in itself a finding about the gene and the disease.
ovarian tumor (continued). "To investigate the functional contribution of claudin-4 to ovarian tumor cell behavior, we disrupted claudin-4 in two ways." (PMID 27724921, 2016). "Western blot analysis revealed that native SKOV3, OVCAR3, and PEO4 ovarian tumor cells expressed claudin-4." (PMID 27724921, 2016). "Stewart and colleagues found that claudin-4 was one of the most highly upregulated (7.5-fold increase) proteins expressed by cisplatin resistant IGROV-1 ovarian tumor cells compared to their cisplatin-sensitive counterparts." (PMID 27724921, 2016). "Together, these observations provide evidence that high claudin-4 expressing ovarian tumor cells have the tumor regenerating properties of cancer stem cells and are associated with cisplatin resistance and enhanced migration." (PMID 27724921, 2016). "Others have observed high claudin-4 expression in ovarian tumor cells that are resistant to chemotherapeutic agents such as cisplatin and paclitaxel." (PMID 27724921, 2016). "Our results suggest that claudin-4 functionally contributes to ovarian tumor cell apoptosis resistance and migration and that disrupting these functions can reduce ovarian tumor burden in vivo." (PMID 27724921, 2016). "SKOV3 and OVCAR3 human ovarian tumor cell lines were used to examine the effect of claudin-4 activity and expression on tumor cell motility." (PMID 27724921, 2016). "To begin to answer this question we investigated the functional significance of claudin-4 in ovarian tumor cells both in vitro and in vivo." (PMID 27724921, 2016). "Results from this study provide key observations that support a functional role for claudin-4 expression in ovarian tumor cell survival and spread." (PMID 27724921, 2016). "Notably, claudin-4 is known to be localized in the nucleus of ovarian tumor cells, where we observed an inverse relationship between claudin-4 expression and lamin B1 nuclear localization." (PMID 39625235, 2025). "We analyzed claudin-4 expression in human ovarian tumors using TCGA to support these findings." (PMID 39625235, 2025). "Notably, our BioID analysis also identified NDRG1 as a potential claudin-4-interating protein in ovarian tumor cells, with more than twice the number of peptides identified for this protein compared to control cells." (PMID 38867360, 2024). "These co-expressions may be associated with their OV related function, namely the ovarian tumor cell apoptosis resistance, migration and targeting extracellular loop interactions of claudin-4 may have therapeutic implications for reducing ovarian tumor burden." (PMID 30796309, 2019). "Casagrande and colleagues have demonstrated the clostridium perfringens enterotoxin (CPE), recognizing a sequence in the second extracellular loop adjacent to the sequence recognized by DFYNP, is cytotoxic to the high claudin-4 expressing stem-like CD44+ ovarian tumor cells." (PMID 27724921, 2016). "Claudin-4 functionally contributes to both ovarian tumor cell apoptosis resistance and migration and targeting extracellular loop interactions of claudin-4 may have therapeutic implications for reducing ovarian tumor burden." (PMID 27724921, 2016). "Although it is clear that claudin-4 plays a role in regulating nuclear size and that CMP can moderate its effects, this finding highlights the intertumoral diversity of ovarian tumor cells, suggesting cell line–specific effects." (PMID 39625235, 2025). "In ovarian tumours, the same group suggested that CLDN3 and CLDN4 are required for signalling through survival or proliferative pathways." (PMID 15743508, 2005). "Thus, claudin-4’s effect on nuclear structure remodeling is feasible and is related to the cell cycle, potentially by altering the dynamics of the nuclear lamina and perinuclear F-actin, which may support genome stability and therapy resistance in ovarian tumor cells." (PMID 39625235, 2025).
ovarian tumor (continued). "Additionally, all ovarian tumor cells treated with CMP showed a pattern of reduced perinuclear F-actin localization, suggesting that both expression and proper claudin-4 localization are required for perinuclear F-actin accumulation." (PMID 39625235, 2025). "Furthermore, exposing Clostridium perfringens enterotoxin (CPE), a potent cytolytic toxin, to its natural receptors Cldn3 and Cldn4 has been shown to induce CPE-mediated cytotoxicity in prostate cancer cells and ovarian tumors." (PMID 35006480, 2021). "Here, we have studied claudin-4 activity in SKOV3, OVCAR3, and PEO4 ovarian tumor cell lines." (PMID 27724921, 2016). "Recent work in the Mor and Santin laboratories has shown that high claudin-4 gene and protein expression are found in a population of CD44 positive (CD44+) ovarian tumor cells exhibiting stem cell-like properties as well as resistance to carboplatin and paclitaxel." (PMID 27724921, 2016). "Of importance, the CD44+ population has significantly higher levels of claudin-4 compared to CD44 negative (CD44−) ovarian tumor cells isolated from the same tumor." (PMID 27724921, 2016). "Contrary to the findings in ovarian tumours reported by Rangel and coworkers that CLDN3 and CLDN4 exhibited cytoplasmic staining and that over-expression of these proteins were associated with malignancy, in our study in breast we did not observe clear positivity of CLDNs in cytoplasm." (PMID 15743508, 2005).
bladder cancer (12 papers, 2014 to 2026). "In urothelial bladder cancer, hypomethylation of the CLDN4 promoter region was associated with cancer metastasis, and so hypermethylation of CLDN4 represents a new potential target of therapy for bladder cancer." (PMID 38731853, 2024). "As a result, expression levels of CASK (p = 0.024), LAMA2 (p = 0.040), LY6D (p = 0.018), and CLDN4 (p = 0.043) were significantly associated with the overall survival of patients with urinary bladder carcinoma." (PMID 30699951, 2019). "In bladder cancer, expression of CLDN4 is associated with chemotherapeutic resistance, and anti-CLDN4 antibody increases chemotherapeutic sensitivity." (PMID 31040910, 2019). "In contrast, bladder cancer shows a clear correlation between CLDN4 expression and parameters associated with cancer progression." (PMID 30647838, 2018). "In bladder cancer, CLDN4 promoter DNA hypomethylation was shown to correlate with CLDN4 overexpression, high-grade tumors, and invasion, and the increase in CLDN4 promoted anti-apoptosis, stemness, and epithelial-mesenchymal transition (EMT)." (PMID 36982569, 2023). "In contrast, CLDN4 hypomethylation and CLDN4 overexpression have been reported in gastric, breast, ovarian, and bladder cancers." (PMID 36982569, 2023). "Specifically, claudin-4 is overexpressed in low/medium-grade bladder carcinomas and becomes underexpressed in high-grade tumors." (PMID 38188015, 2023). "In the present study, CLDN4 promoter hypomethylation induced CLDN4 overexpression in bladder cancer." (PMID 35742959, 2022). "Claudin-4 is a marker of bladder epithelial differentiation, and abnormal claudin-4 expression in bladder cancer is related to local invasion, lymph node metastasis, and distant metastasis." (PMID 33767583, 2021). "We recently developed a monoclonal antibody specific to the extracellular domain of CLDN4, named 4D3, which exerts antitumoral effects in bladder cancer models." (PMID 30647838, 2018). "For example, the claudin-4 gene is hypermethylated in bladder carcinomas." (PMID 38188015, 2023). "CLDN4 is overexpressed in bladder cancer due to promoter DNA hypomethylation." (PMID 36982569, 2023). "Importantly, we showed that the generated anti-CLDN4 antibody (clone 4D3) was capable of enhancing anti-cancer effects induced by CDDP treatment in bladder cancer." (PMID 31040910, 2019).
prostate carcinoma (12 papers, 2006 to 2026). A carcinoma that arises from epithelial cells of the prostate gland. "Such apparent miss-localizations were also described for the CLDN-4 protein in human prostate cancer-derived cell lines and may be related to the loss of cellular organization due to a defect in tight-junction formation or cell polarity—features common in tumor cells." (PMID 34830170, 2021). "Herein, we showed that knocking down Cldn3 or Cldn4 expression in prostate cancer cells decreased cell survival." (PMID 35006480, 2021). "The goal of our study was to examine the differences in Cldn3 and Cldn4 protein levels according to growth characteristics of prostate cancer cells." (PMID 35006480, 2021). "The expression of Cldn3 and Cldn4 is tissue specific and has been described to be up-regulated in ovarian, breast, and prostate cancers." (PMID 35006480, 2021). "We and others have shown that there are higher levels of Cldn3 and Cldn4 in metastatic human prostate cancer cells than in normal human prostate cells." (PMID 35006480, 2021). "Knocking down Cldn3 and Cldn4 expression appears to be androgen independent as both human prostate cancer cell lines PC3 (androgen independent) and LNCaP (androgen dependent) had similar growth outcomes." (PMID 35006480, 2021). "Herein, we target Cldn3 and Cldn4 expression in prostate cancer cells using Cldn3 and Cldn4 siRNAs and assess its impact on cell growth, migration, viability, and clonogenic survival." (PMID 35006480, 2021). "Although Cldn3 and Cldn4 have been shown to be expressed in prostate cancers, and was the focus of CPE intervention, targeting Cldn3 and Cldn4 expression in relation to prostate cancer cell survival rates has not been investigated." (PMID 35006480, 2021). "Previously, we found that Cldn3 and Cldn4 are expressed in aggressive high-grade human prostate cancer specimens." (PMID 35006480, 2021). "Cldn3/Cldn4 siRNA treatment resulted in a greater than 85% decrease in the protein levels of Cldn3 and Cldn4, which was accompanied by a 30–40% decrease in prostate cancer cell growth and a 60–65% reduction in cell viability." (PMID 35006480, 2021). "Western blots show that Cldn3 and Cldn4 levels are higher in metastatic prostate cancer cells (PC3, LNCaP, and DU145) compared to normal prostate cells (RWPE-1)." (PMID 35006480, 2021). "Claudin-3 and claudin-4 are the most frequently deregulated in cancers and are found highly expressed in ovarian, breast, and prostate cancers." (PMID 32197343, 2020). "Specifically, we generated a Cldn3 knockdown of 85% and 97% for PC3 and LNCaP human prostate cancer cells, respectively, when treated with siCldn3_4 and a Cldn4 knockdown of > 99% and 98% for PC3 and LNCaP human prostate cancer cells, respectively, when treated with siCldn4_1." (PMID 35006480, 2021). "Knocking down Cldn3/Cldn4 affects prostate cancer cell growth and survival and may have therapeutic implications." (PMID 35006480, 2021). "In addition, Cldn4 is overexpressed in primary and metastatic prostate cancer, and Cldn3 is strongly expressed in the majority of prostate cancers." (PMID 35006480, 2021). "The similar expression patterns of Cldn3 and Cldn4 in prostate cancers may suggest a coordinated regulation and raises the possibility for an effective targeted treatment strategy." (PMID 35006480, 2021). "In addition, we confirmed that Cldn4 is expressed in higher grade prostate cancer specimens compared to benign prostatic hyperplasia specimens." (PMID 35006480, 2021). "We hypothesize that Cldn3 or Cldn4 may be potential therapeutic targets for the management of prostate cancer." (PMID 35006480, 2021). "Moreover, claudin-3 and claudin-4 have become promising candidates in the new treatment strategy against prostate cancer." (PMID 32197343, 2020). "This suggests that claudin-4 may play a role in the early stages of prostate cancer development." (PMID 38188015, 2023).
prostate carcinoma (continued). "In examining the protein levels of Cldn3 and Cldn4 after 72 h, we generated a knocked down of greater than or equal to 70% for both PC3 and LNCaP human prostate cancer cells when treated with siCldn3s and siCldn4s." (PMID 35006480, 2021). "Based on the knockdown of Cldn3 and Cldn4 using PC3 and LNCaP prostate cancer cells, siCldn3_4 and siCldn4_1 were selected for all subsequent functional studies." (PMID 35006480, 2021). "Furthermore, decreasing the level of CLDN3 and CLDN4 proteins through knockdown of CLDN3 and CLDN4 in prostate cancer resulted in a 30–40% decrease in prostate cancer cell growth, a 60–65% reduction in cell viability, and cell migration." (PMID 38731853, 2024). "The result of targeting Cldn3 and Cldn4 expression on the growth and viability of prostate cancer cells has not been elucidated." (PMID 35006480, 2021).
breast tumors (10 papers, 2005 to 2024). "An in vivo assay in nude mice was transplanted by CLDN-4-silenced MCF-7 cells indicated the regression in breast tumor size." (PMID 33407452, 2021). "This is in agreement with numerous studies that have shown CLDN4 to be overexpressed in pancreatic, ovarian, and breast tumors relative to normal tissue." (PMID 31217513, 2019). "We tested this profile (TN and low expression of at least two of four epithelial cell-cell adhesion markers; claudin 3, claudin 4, claudin 7 and E-cadherin) in a large cohort of breast tumors with long-term follow up." (PMID 28045912, 2017). "We first used immunostaining to localize claudin-4 in both normal mammary epithelial cells and breast tumor cells." (PMID 23521713, 2013). "Using serial analysis of gene expression (SAGE), Kominsky and coworkers have shown both that claudin-4 is expressed in the majority of breast tumors tested and that expression is increased 2–3 fold compared to normal breast tissue." (PMID 23521713, 2013). "CLDN4 positivity was present in all 56 tissue sections in epithelial cell membranes as well as in the frozen section and breast tumour array analyzed by confocal microscopy." (PMID 15743508, 2005). "In addition, these tumors had low expression of claudin 3 and claudin 4, possibly implying the claudin-low subtype of breast tumor." (PMID 25938540, 2015). "Although the similar CLDN3 and CLDN4 TJ proteins are highly expressed in breast neoplasia, we hypothesize that mechanisms other than alteration in TJs are involved in the loss of CLDN1 expression in breast tumours." (PMID 15743508, 2005). "This cluster had low expression of the claudin genes CLDN3, CLDN4, and CLDN7, raising the possibility that tumors in this cluster were members of the claudin-low subtype, a group of breast tumors known for their invasive, mesenchymal-like behavior." (PMID 23667446, 2013). "This revealed that both EPI (e.g. LLGL2, CLDN4, KRT7, ST14) and MES (e.g. SNAI1, VIM, AP1M1) genes positively correlated with PIEZO1 expression across all quintiles, whilst markers of luminal breast tumors (ESR1, FOXA1, PGR) negatively correlated in all instances." (PMID 38632473, 2024). "In this study we have shown that claudin-4 can be found in puncta along cellular projections of non-confluent normal mammary epithelial cells as well as breast tumor cells." (PMID 23521713, 2013). "Expression of Claudin-4, EGFR, CAIX, GLUT-1 and IGF1R was assessed by immunohistochemistry on tissue microarrays composed of 97 paired primary breast tumors and their distant (non-bone) metastases." (PMID 25417118, 2014).
lung carcinoma (10 papers, 2017 to 2025). "We generated a claudin-4-specific CAR construct and validated its antigen specificity in vitro using SU86.86 cells (claudin-4+) and H522 lung cancer cells (claudin-4-)." (PMID 40666525, 2025). "As a result, Claudin-4 is a helpful marker for differentiating reactive or malignant mesothelial cells from lung cancer." (PMID 40091315, 2025). "On the other hand, there was a statistically significant difference in the immunoexpression of Claudin-4 between lung cancer, benign effusion with RMCs, and MPM (p value <0.001)." (PMID 40091315, 2025). "Tested lung cancer cell lines expressed not only Cldn1, but also Cldn3, Cldn4, and Cldn7 (PC‐9 cells) or Cldn3 (SK‐Mes‐1 cells)." (PMID 31825142, 2020). "Nonetheless, the biological function of CLDN4 on the development or progression of lung cancer still remained largely unknown, especially on its related comorbidity, MPE." (PMID 38629624, 2024). "CLDN-4 affects the malignancy of various cancers, including lung cancers." (PMID 38338691, 2024). "Claudin-4 was negative in 25/25 (100%) of MPM cases and positive in 37/39 (94.9%) of lung cancer cases." (PMID 40091315, 2025).
metastatic carcinoma (10 papers, 2008 to 2025). A carcinoma which has spread from the original site of growth to another anatomic site. "The results demonstrated that while all metastatic carcinomas showed membrane Claudin-4 staining, all reactive and malignant mesothelial cells tested negative for the protein." (PMID 40091315, 2025). "The expression of CLDN4 has been shown to be both sensitive and specific in detecting metastatic carcinomas, while excluding mesothelial proliferations." (PMID 40687428, 2025). "When it came to differentiating MPM from metastatic cancer, Claudin-4 IHC staining demonstrated 100% sensitivity, specificity, PPV, NPV, and DA (diagnostic accuracy), with a statistically significant p value (p<0.00001)." (PMID 40091315, 2025). "The sensitivity for metastatic carcinoma detection from effusion/peritoneal washing was 100, 97.64 and 88.23% for claudin-4, MOC-31 and p16, respectively." (PMID 32178642, 2020). "Results revealed a higher Mesenchymal markers in primary cancer cells (e.g., NCAM1, LAMB1, SERPINE1, TCF4, VIM, ZEB1, and ZEB2) and a higher Epithelial markers in metastatic cancer cells (e.g., CDH1, CLDN4, ELF3, EPCAM, KRT18, KRT7, and KRT8)." (PMID 37202394, 2023). "In a practical algorithm, BAP1 and claudin-4 seems to represent the best panel for differentiating MPM with epithelioid features and metastatic carcinoma either on cytology or biopsy." (PMID 34070888, 2021). "As such, if a laboratory has a tested and established protocol for MOC31, it may not be recommendable to simply replace MOC31 with claudin-4, but to complement the detection of metastatic carcinoma by both markers." (PMID 41225968, 2025). "The cell cluster C1, classified as Epithelial Cell Adhesion Molecule (EpCAM)+ metastatic cancer cell and correlated with activation of tight junction and adherence junction, was significantly enriched in the recurrent MPE group, in which Claudin‐4 (CLDN4) was identified." (PMID 38629624, 2024).
serous ovarian cancers (8 papers, 2009 to 2025). "We have previously performed an immunohistochemical analysis of the expression of CLDN3 and CLDN4 in the Fallopian tubes of 6 patients with serous ovarian cancer and found that both the distal Fallopian tubes and serous ovarian cancers themselves expressed these two proteins in abundance." (PMID 23805314, 2013). "Moreover, since the patients included in this study were restricted to those with late stages, high grade serous ovarian cancers, further studies with a larger cohort will be necessary to clearly assess the potential of claudin-4 in other subtypes, in low grades, and in early stages patients." (PMID 19619303, 2009). "SCCOHT primary tumors lacked expression of Claudin-4 (average H-Score = 0), whereas High-Grade Serous Ovarian Cancer (HGSC) tumors had a dynamic range of expression with some expressing very strongly." (PMID 33355532, 2020).